AK4 (adenylate kinase 4)
Diseases named in the same sentence as AK4 in open-access papers (continued):
Sharing a sentence is not in itself a finding about the gene and the disease.
esophageal cancer (5 papers, 2018 to 2021). A primary or metastatic malignant neoplasm involving the esophagus. "Further, AK4, a radioresistant protein in esophageal cancer, was revealed in our study to bind with hnRNPC protein and its stability was enhanced by LINC00662." (PMID 32549791, 2020). "MiR-199a-3p targets AK4 to modulate the radioresistance of esophageal cancer cells." (PMID 32549791, 2020). "Besides, AK4 has been uncovered to be involved in the radio-resistance of esophageal cancer cells." (PMID 31931771, 2020). "High expressions of AK4 also promote cell proliferation and invasion in ovarian cancer and HER2 positive breast and esophageal cancers." (PMID 34217310, 2021).
lung adenocarcinoma (5 papers, 2019 to 2023). A carcinoma that arises from the lung and is characterized by the presence of malignant glandular epithelial cells. "AK4 is upregulated in lung adenocarcinomas compared to that in normal cells, and high AK4 expression has been reported to be associated with advanced stage, disease recurrence, and poor prognosis." (PMID 36982634, 2023). "By this means, we identified 1501 probes that were significantly associated with AK4 expression in lung adenocarcinoma patients." (PMID 30696468, 2019). "A consensus 118-gene signature of AK1 and AK4 was identified as a co-expressed gene set that is significantly associated the prognosis of lung adenocarcinoma patients." (PMID 31444368, 2019). "Furthermore, CRABP2, DHCR24, and AK4 are useful IHC markers for diagnosis of lung adenocarcinoma invasiveness and may be associated with malignant progression of AIS." (PMID 37004157, 2023). "Expression of CRABP2, DHCR24, and AK4, and clinicopathological features in patients with lung adenocarcinoma." (PMID 37004157, 2023). "The existence of an AK4-HIF-1α feedforward loop has been recently shown in a human lung adenocarcinoma cell lines and in murine M1 macrophages." (PMID 34638712, 2021). "We found that HIF-1α activity is significantly activated in lung adenocarcinoma patients with an AK4 metabolic gene signature." (PMID 30696468, 2019). "Immunohistochemistry (IHC) analyses in 140 lung adenocarcinoma patients showed overexpression of AK4 significantly correlated with worse overall survival (P = 0.001) whereas overexpression of AK1 significantly associated with good prognosis (P = 0.009)." (PMID 31444368, 2019). "In this study, we have identified a consensus gene set derived from AK4- and AK1-associated gene expression signature in lung adenocarcinoma." (PMID 31444368, 2019). "In our analyses, we found overexpression of AK4 and downregulation of AK1 are associated with poor prognosis in lung adenocarcinoma." (PMID 31444368, 2019). "Meanwhile, we also identified the consensus AK4 metabolic gene signature between the GSE31210 lung adenocarcinoma dataset and TCGA LUAD dataset and found that HIF-1α was again significantly activated, with an activation z score of 4.098." (PMID 30696468, 2019). "However, the opposite correlation of AK1 and AK4 was obviously in the TCGA lung adenocarcinoma cohort (both P < 0.001)." (PMID 31444368, 2019). "By analyzing gene expression signatures of AK family in TCGA lung adenocarcinomas, we surprisingly found that target genes of “SCC” marker p63 (TP63) were increasingly upregulated upon the over-expression of AK4 and the under-expression of AK1." (PMID 31444368, 2019). "Through ingenuity upstream regulator analysis of the AK4 metabolic signature, we also found that NRF2, the master regulator of antioxidant responses, was significantly activated, suggesting that high AK4 expression lung adenocarcinoma patients may be accompanied by NRF2 activation." (PMID 30696468, 2019).
ovarian carcinoma (4 papers, 2021 to 2023). A malignant neoplasm originating from the surface ovarian epithelium. "For instance, miR‐3666 targets STAT3 and modulates the activity of AK4, exhibiting a suppressive role in ovarian cancer." (PMID 34890108, 2022).
bladder cancer (3 papers, 2021 to 2023). "Increased AK4 expression is observed in patients with bladder cancer and is associated with poor prognosis, while its inhibition in bladder cancer cell lines is associated with the suppression of cancer cell growth and decreased metastasis." (PMID 36982634, 2023).
glioma (3 papers, 2020 to 2023). A benign or malignant brain and spinal cord tumor that arises from glial cells (astrocytes, oligodendrocytes, ependymal cells). "AK4 regulates AMPK signaling and its expression is significantly correlated with survival of glioma patients." (PMID 32549791, 2020).
cervical cancer (2 papers, 2021). A primary or metastatic malignant neoplasm involving the cervix. "The functional study shown that expression of AK4, HK2, P4HA1, TGFBI and VEGFA can regulate the proliferation, migration, and invasion ability of cervical cancer cells in vitro." (PMID 34217310, 2021). "The functional study shown that expression of AK4, HK2, P4HA1, TGFBI and VEGFA can regulate the proliferation, migration, and invasion ability of cervical cancer cells." (PMID 34217310, 2021). "The results obtained with RT-PCR and immunohistochemistry assays both showed that AK4, HK2, P4HA1, TGFBI and VEGFA were all highly expressed in these cervical cancer tissue samples." (PMID 34217310, 2021). "Among them, AK4, P4HA1 and TGFBI were first confirmed as oncogene in cervical cancer." (PMID 34217310, 2021). "The colony formation and transwell assays results showed that reduced AK4, HK2, P4HA1, TGFBI and VEGFA expression, which significantly inhibited proliferation, migration and invasion ability of cervical cancer cells." (PMID 34217310, 2021). "Moreover, the results of qPCR and immunohistochemistry staining assay revealed that the expression of AK4, HK2, P4HA1, TGFBI and VEGFA is high in cervical cancer." (PMID 34217310, 2021). "Furthermore, to verify the accuracy of the 5-gene signature, we examined the expression of the signature genes (AK4, HK2, P4HA1, TGFBI and VEGFA) in clinical samples from 10 cervical cancer patients by qPCR and IHC analysis." (PMID 34217310, 2021). "Moreover, the result of RT-PCR and immunohistochemistry demonstrated that AK4, HK2, P4HA1, TGFBI and VEGFA were all highly expressed in these cervical cancer tissue samples." (PMID 34217310, 2021).
colorectal cancer (2 papers, 2021 to 2022). A primary or metastatic malignant neoplasm that affects the colon or rectum.
non-small cell lung carcinoma (2 papers, 2021). A group of at least three distinct histological types of lung cancer, including non-small cell squamous cell carcinoma, adenocarcinoma, and large cell carcinoma. "A previous study showed in non-small cell lung cancer cells (NSCLC) that Ak4 stabilizes Hif1α protein through inhibition of prolyl hydroxylase (PHD), our data suggest that Ak4 not only stabilizes Hif1α protein but also enhances its transcription." (PMID 33790902, 2021). "Targeting the AK4-HIF-1α axis has been proven to be a potent therapeutic strategy in non-small-cell lung carcinoma." (PMID 34638712, 2021).
cognitive decline (1 paper, 2025). "In contrast, Rapid Decline showed increased β-amyloid (bA), glial and inflammatory markers (CD44, PLXNB1), and stress- and mitochondrial-related proteins (GSTP1, AK4, HSPB2, FBXO2, IGFBP5), which have been associated with neurodegeneration and cognitive decline in AD." (PMID 40799531, 2025).
colon cancer (1 paper, 2022). "Resveratrol was studied in vitro on AK4-knockdown colon cancer cells (SW480 and SW620) and showed that it could diminish the invasion and metastasis of colon cancer cells by reversing the expression of EMT (epithelial–mesenchymal transition) markers via the AKT/GSK-3β/Snail pathway." (PMID 36142147, 2022).
head and neck cancer (1 paper, 2025). A primary or metastatic malignant neoplasm affecting the head and neck. "Furthermore, high expression of AK4 was correlated with worse prognosis in patients with head and neck cancer patients compared with low expression of AK4." (PMID 40593461, 2025).
heart failure (1 paper, 2020). Inability of the heart to pump blood at an adequate rate to meet tissue metabolic requirements. "In this study, AK4 and HIF-1a showed a downward trend, while Nrf2, SOD, and CytC showed a significant downward trend, indicating that oxidative stress played a crucial role in heart failure." (PMID 33362553, 2020).
idiopathic pulmonary arterial hypertension (1 paper, 2021). A sporadic form of pulmonary arterial hypertension (PAH) characterized by elevated pulmonary arterial resistance leading to right heart failure. "Finally, we show that AK4 levels are elevated in pulmonary vessels from patients with idiopathic pulmonary arterial hypertension (IPAH), and AK4 silencing decreases glycolytic metabolism of IPAH-PASMCs." (PMID 34638712, 2021).
liver cancer (1 paper, 2021). An epithelial or non-epithelial malignant neoplasm that arises from the liver. "Interestingly, AK4 was downregulated by hypoxia in a human liver cancer cell line, HepG2." (PMID 34638712, 2021).
lymph node metastasis (1 paper, 2023). "Furthermore, the expressions of CRABP2 and AK4 were also significantly correlated with lymph node metastasis." (PMID 37004157, 2023).
pancreatic adenocarcinoma (1 paper, 2023). "A positive correlation of AK4P1 with AK4 in pancreatic adenocarcinoma was observed." (PMID 36476264, 2023). "Thus, we explored the relationship between AK4P1 and its parental gene AK4 in pancreatic adenocarcinoma." (PMID 36476264, 2023). "Finally, AK4P1 might also exert its effects by interacting with oncogenic parental gene AK4 in pancreatic adenocarcinoma." (PMID 36476264, 2023).
Parkinson disease (1 paper, 2016). A progressive degenerative disorder of the central nervous system characterized by loss of dopamine producing neurons in the substantia nigra and the presence of Lewy bodies in the substantia nigra and locus coeruleus. "Abnormal expression of AK4 are proven in a variety of diseases, such as Parkinson's disease, lung tumors and so on." (PMID 27402083, 2016).
cancer (25 papers, 2013 to 2025). A tumor composed of atypical neoplastic, often pleomorphic cells that invade other tissues. "In cancer, AK4 upregulation is associated with metabolic reprogramming, tumor progression, and metastasis." (PMID 34638712, 2021). "For proteomics verification, 2 genes (UACA and AK4) identified to be closely related to cancer, according to the results of association analysis, were subjected to western blot." (PMID 34637398, 2021). "Many studies have demonstrated that AK4 regulates the sensitivity of cancer cells to antitumor drugs and radiation therapy." (PMID 40593461, 2025). "AK4 localization to the mitochondria and induction of its expression by hypoxia suggests that AK4 is involved in the malignant transformation and metastasis of cancer." (PMID 36982634, 2023). "A relationship between AK4 and cancer has been reported, and it is suggested to be a carcinogenic or therapeutic target." (PMID 36982634, 2023). "The knockdown of AK4 in cancer cells and further gene expression and metabolomic analyses revealed that it is important for the regulation of mitochondrial activity and that AK4 knockdown increases cancer drug sensitivity." (PMID 36982634, 2023). "Inhibition of METTL3 in tamoxifen-resistant cancer cells can lead to the decrease of AK4, which further promotes the apoptosis of mitochondrial, thus attenuates resistance to tamoxifen." (PMID 35022030, 2022). "Recent, in vitro experiments on cancer cells have demonstrated that AK4 silencing increases intracellular ATP and decrease ATP/ADP ratio which leads to AMPK activation." (PMID 35712500, 2022). "They found that in cancer cells silencing of AK4 gene increase intracellular ATP level as well as ATP/ADP ratio via enhancing glycolytic flux." (PMID 35712500, 2022). "In cancer, AK4 has been suggested to contribute to progression and metastasis, though the exact mechanism is not clear." (PMID 35756609, 2022). "Similar effects of AK4 targeting have been described for immortalized human embryonic kidney cells and some cancer cell lines." (PMID 34638712, 2021). "The most extensive research on the function of this AK isoenzyme has been performed on cancer cells, where AK4 was shown to regulate hypoxia tolerance, cell proliferation and viability, mitochondrial activity, metastasis, and anti-cancer drug sensitivity." (PMID 34638712, 2021). "Studies have shown that AK4 plays a role in the occurrence and development of cancer, which is why it is a potential target for anti-cancer therapy." (PMID 34637398, 2021). "Adenylate kinase 4 (AK4) is a member of the adenosine kinase family and has been found to play an important role in malignant tumors and anti-tumor therapy." (PMID 34217310, 2021). "We particularly focused on possible effects of AK4 on proliferation and energy metabolism of PASMCs in order to provide new insights into the altered cellular metabolism and cancer-like pathways in PH." (PMID 34638712, 2021). "As an isoform of this enzyme, adenylate kinase 4 (AK4) has been demonstrated as a carcinogen, and plays crucial role in cancer cell resistance to radiation or drugs." (PMID 32549791, 2020). "More importantly, previous investigations have confirmed the involvement of AK4 in chemoresistance of cancers." (PMID 31931771, 2020). "Fujisawa and colleagues in 2016 have proposed that there are two mechanisms how AK4 regulates mitochondrial respiration in cancer cells." (PMID 32509571, 2020). "AK4 was reported to be involved in the development of cancers, and is used as a potential therapeutic target for anticancer treatment." (PMID 29866054, 2018). "AK4 contributes to cancer process by maintaining the proper balance of adenosine nucleotides and by controlling the bioenergetic program switch of cancer cells." (PMID 29584711, 2018). "Among them, we choose the AK4 gene as our target, which was previously found to be related to cancer drug resistance." (PMID 29866054, 2018).
cancer (continued). "Further investigations in EC cells found that the miR-199a-3p targets AK4, which was reported to be involved in stress, drug resistance, malignant transformation in cancer." (PMID 30479565, 2018). "We further revealed that miR-199a-3p targets the AK4 gene, which was reported to be involved in stress, drug resistance, malignant transformation in cancer." (PMID 29866054, 2018). "AK4 knockdown cells treated with short hairpin RNA increased ATP production and showed greater sensitivity to hypoxia and anti-cancer drug, cis-diamminedichloro-platinum (II) (CDDP)." (PMID 26980435, 2016). "An isoform of this enzyme, adenylate kinase 4 (AK4), is localized in the mitochondrial matrix and is believed to be involved in stress, drug resistance, malignant transformation in cancer, and ATP regulation." (PMID 26980435, 2016). "AK4 is implicated in hypoxia responses and metabolic reprogramming in cancer; however, its function in normal (non-cancerous) human cells remains largely elusive." (PMID 34638712, 2021). "This points to a common fundamental role of AK4 in cancer cells and PASMCs." (PMID 34638712, 2021). "Also, there is evidence that another mitochondrial isoform, AK4, is involved in the regulation of mitochondrial metabolism in cancer cells." (PMID 34381722, 2021). "As AK4 was reported to modulate the radioresistance of cancer cells, we guessed that AK4 might participate in LINC00662-mediated radioresistance in OSCC cells." (PMID 32549791, 2020). "Moreover, new data indicate that AK4 was shown to be involved in the radioresistance of esophageal cancer cells and in chemoresistance of other cancers." (PMID 32509571, 2020). "The oncogenic potential of many cancers has been related with high levels of AK4." (PMID 29584711, 2018). "For example, the AK4 expression level could modulate the anti-cancer drug sensitivity through regulating mitochondrial activity." (PMID 29866054, 2018). "In conclusion, our findings indicated that the AK4 expression level could modulate the anti-cancer drug sensitivity through regulating mitochondrial activity." (PMID 26980435, 2016). "In BC, METTL3 increases adenylate kinase 4 (AK4) expression to elevate ROS and p38 activity and augment tamoxifen resistance in cancer cells." (PMID 38721006, 2024). "In support of our findings, AK4 has also been found to be overexpressed in human HCC-derived HepG2 cells, as well as other cancer types from a diverse group of tissues." (PMID 35756609, 2022). "Further, AK4 expression is induced by hypoxia, and protein complex AK4-ANT-VDAC-HK2 complex supports the high glycolytic activity of cancer cells." (PMID 34381722, 2021). "Specifically, we will overview how AK isoforms, localized in mitochondria (AK2 and AK4), and their main communication partners cytosolic AK (AK1 and AK6) are involved in cancer formation and metastasis." (PMID 32509571, 2020). "Studies indicate that AK isoforms (AK1, AK2, AK4, and AK6) have an important role in the regulation of cancer cell metabolism, metabolic signaling, and cell migration and invasion." (PMID 32509571, 2020). "First, in cancer cells, AK4 interacts with ANT, which forms with voltage-dependent anion channel (VDAC) and HK transmembrane complex AK4-ANT-VADC-HK." (PMID 32509571, 2020). "In addition, hnRNP C can enhance the radioresistance of OSCC cells by interacting with lncRNA LINC00662 to stabilize adenylate kinase 4 (AK4) mRNA and increase the expression of AK4 protein, which is a key enzyme in cancer cell resistance to radiation." (PMID 36505770, 2022).